EDN1 (endothelin 1)
Diseases named in the same sentence as EDN1 in open-access papers (continued):
Sharing a sentence is not in itself a finding about the gene and the disease.
tumor (continued). "To date, most reports have focused on the oncogenic potential of EDN1 and EDN2, both of which are overexpressed in various tumour entities." (PMID 19527488, 2009). "Previously, EDN1 and EDN2 were found to be commonly overexpressed in a broad range of human tumour entities." (PMID 19527488, 2009). "The effects of tumour cells (Colon 26) on the development and response of new blood vessels to different vasoconstrictors (platelet activating factor; PAF, endothelin-1, angiotensin II, adrenalin and 5-hydroxytryptamine) have been investigated." (PMID 1384642, 1992). "Therefore, the present study suggests that NCAPD3-knockdown-induced differentially expressed genes (DEGs) such as CRNDE, EDN1, and JUNB can regulate cell and tumor invasion through EGFR and PLAUR." (PMID 38711992, 2024). "The sub‐clustering of ECs revealed six subtypes, including extra‐alveolar capillary EC (cEC) (FCN3+EDN1+PLVAP+), alveolar cEC (HPGD+EDNRB+IL1RL1+), arterial EC(GJA5+FBLN5+DKK2), lymphatic EC (CCL21+TFF3+FABP4), INSR+ tumour EC (INSRhiHSPG2+PLVAP+), and ACKR1+ tumour EC (ACKR1+SELP+IL1R1+)." (PMID 35184398, 2022). "JMJD1A increases or maintains expression of certain genes under hypoxia by reducing H3K9 demethylation of specific hypoxia-responsive promoters, including ADM, EDN1, HMOX1, and GDF15, resulting in increased expression of these genes and favouring tumour cell growth." (PMID 34572020, 2021). "Additionally, the HIF-1-regulated vascular tone-modulating endothelin 1 (EDN1) and heme oxygenase 1 (HMOX1) transcripts were significantly suppressed throughout the entirety of LUAD tumor development." (PMID 34940617, 2021). "When Roquin2 and EDN1/PDGFC were co-knockdown, HUVEC migration was restored to comparable to the scramble control group, suggesting that the angiogenic genes are indeed involved in Roquin2-mediated tumor angiogenesis." (PMID 34345214, 2021). "HIF-2α transcriptional targets EDN1, EPO, GNA14, and VEGFA were significantly upregulated in the tumor bed but not the surrounding liver tissue, indicating hyperactivation of the hypoxia signaling pathway within the tumor." (PMID 32235007, 2020). "For example, VEGF, endothelin-1 (ET-1), and EGFL7 are tumor-secreted proteins that decrease cellular adhesion molecule (CAM) expression by tumor endothelium, which in turn blocks T cell transendothelial migration and subsequent trafficking of T cells into tumors." (PMID 32117236, 2020). "EDN1, ITGB3, and F3 have been implicated in tumor progression, but they have not been well studied with respect to DS." (PMID 32934781, 2020). "Additionally, the tumour endothelium expresses molecules that can block T-cell infiltration in different tumour types (including melanoma), such as FasL, endothelin B receptor (ETBR), and endothelin-1." (PMID 31212986, 2019). "The endothelin-1 (ET-1) is a neurotransmitter that is secreted by neuronal cells, non-neuronal cells, and tumor cells." (PMID 30443456, 2018). "In this study, overexpression miR-1 in GC cells affected the endothelial cell tubular formation activity in a co-culture system study, implying that miR-1 may modulate gastric-tumor-related angiogenesis by regulating VEGF-A and EDN1." (PMID 28493075, 2018). "Stains for THBS1, JAG1, and EDN1 were available in the protein atlas database for the same tumor and showed significant expression of all three genes from our CINP transcriptional module in the VM tumor tissue but little stain in healthy tissues." (PMID 29162797, 2017). "In conclusion, we found that Sal A is a novel ETA receptor antagonist, and further observed anti-tumor effect with or without exogenous endothelin-1." (PMID 27490540, 2016). "In as much as peritumor tissue-derived CSC presented greater chemoresistance to treatments respect to core tumor derived-CSC, we decided to investigate by RT-qPCR the expression of the main modulators of EMT and/or drug resistance such as TWIST, EDN1 and PRKCA in several samples of GBM CSC." (PMID 27344175, 2016).
tumor (continued). "The clinical implication supports the view that EDN3, in contrast to EDN1 and EDN2, may act as natural tumour suppressor in the human mammary gland." (PMID 19527488, 2009). "Furthermore, NGS analysis revealed that NF-κB/RELA targets including CCL2, CXCL8, EDN1, IL-1β, IL-6, and SERPINE1 were further reduced and several potential tumor suppressors, such as FABP3, FADS2, FDFT1, SEMA6A, and PCK2, were synergistically induced by the Gefitinib-+IKK16 treatment." (PMID 36358633, 2022). "The secretion of IL-6 from MSCs increased the secretion of endothelin-1 (ET-1) in cancer cells, which induced the activation of protein kinase B α (AKT) and ERK in endothelial cells, thereby increasing their ability to recruit and sustain angiogenesis in the tumor." (PMID 35741334, 2022). "On the other hand, in OSCC, tumor progression and metastasis are also sustained by the presence of hypoxia-inducible factor (HIF) and related genes induced by hypoxia, such as VEGF, interleukin 1A (IL-1A), endothelin 1, platelet-derived growth factor B (PDGFB) and erythropoietin (EPO)." (PMID 35890188, 2022). "Since tumors are reported to be hypoxic, even in normoxic animals, one could have expected endothelin-1 secretion and thus macitentan effect on tumor growth in normoxic animals." (PMID 35902610, 2022). "Besides, we also observed that overexpression of EDN1 and PDGFC could reverse the inhibitory effects of Roquin2 on tumor angiogenesis in vitro and in vivo." (PMID 34345214, 2021). "Additionally, the HIF2α transcriptional targets EDN1, EPO, GNA14, and VEGFA were significantly upregulated in the tumor and might also promote tumor progression." (PMID 32235007, 2020). "Recent studies have shown that EDN1 and VEGF-A promoted tumor progression via an angiogenesis-independent action of epithelial–mesenchymal transition, which may provide a plausible explanation for our observations that miR-1 inhibited the proliferation and migration of GC." (PMID 28493075, 2018). "HIF-2α target genes EDN1, EPO, GNA14, and VEGF were significantly upregulated in the tumor bed but not in the surrounding liver tissue." (PMID 32235007, 2020).
cancer (198 papers, 1994 to 2026). A tumor composed of atypical neoplastic, often pleomorphic cells that invade other tissues. "Endothelin-1 (ET-1) is a potent vasoconstrictor which has been implicated in many cancer-promoting mechanisms." (PMID 38540124, 2024). "DMS114 cells with resistance to nintedanib (a kinase inhibitor used to block cancer growth) (DMS114/NIN) portrayed an amplified expression of EDN1 and EDNRA, encoding ET-1 and ETAR, respectively." (PMID 38540124, 2024). "EDN1 in the cancer microenvironment induces mechanical allodynia associated with growth of HSC-3 cells in the mouse hind paw44." (PMID 32895418, 2020). "EDN-1 is an endothelial cell-derived vasoconstrictor peptide that has been associated with the development of several cancers through the activation of pathways involved in cell proliferation, migration, invasion, EMT, osteogenesis and angiogenesis." (PMID 27708222, 2016). "Endothelin-converting enzyme-1 (ECE-1) is the enzyme predominantly responsible for producing active endothelin-1 (ET-1), a mitogenic peptide implicated in the aetiology of a number of diseases, including cancer." (PMID 24497914, 2014). "The association between EDN1 and cancer has been documented with three distinct SNPs: rs5370 (C>A), a missense variation encoding an aspargine (N) instead of a lysine (K); rs1800541 (T>G), an alteration located at the gene promotor; and rs2070699 (G>T), an intronic variation." (PMID 38785560, 2024). "We hypothesized that neutrophils expressing the pro-survival dual endothelin-1/signal peptide receptor, DEspR, are apoptosis-resistant just like DEspR+ cancer cells, hence comprise a consequential pathogenic neutrophil-subset in ARDS and COVID19-ARDS." (PMID 34545358, 2021). "Additionally, Endothelin-1 (EDN1) (4.26-fold increase) encodes a growth factor that is frequently produced by cancer cells and plays a key role in cell growth, differentiation, apoptosis, and tumorigenesis." (PMID 24161199, 2013). "BCAM-induced proteins, previously reported to drive EMT and associated processes such as cell migration in various cancers, include AREG, CXCL1, CXCL10, EDN1, FGF2, TGFβ1 and VEGFB." (PMID 40082910, 2025). "To assess the oncogenic role of EDN1 across malignancies, we analyzed its expression in 18 cancer types using the TCGA dataset." (PMID 41425720, 2025). "ECE1 is a metalloprotease responsible for activating big endothelin-1 (ET-1), a potent vasoconstrictor and mitogen and plays a role in cancer-related properties such as uncontrolled proliferation and invasiveness through the activation of ET-138." (PMID 38062093, 2023). "In a colorectal cancer model, IL6 and angiopoietin 1 secreted by MSCs provoked cancer cells to produce endothelin 1, resulting in the promotion of cancer angiogenesis." (PMID 35629138, 2022). "The role of the endothelin-1 in promoting cancer cell development was investigated using the dual endothelin receptor antagonist, macitentan." (PMID 35902610, 2022). "This mostly occurs via cancer cell-produced endothelin-1 (ET-1), which stimulates endothelin A receptor(ETR) in osteoblasts, activating Wnt signaling and osteoblast activity." (PMID 34440747, 2021). "This suggests that the silencing of RARβ enhances the cancer growth in A549 CD166+EpCAM+ and A549 CD166-EpCAM- cell populations by EDN1 overexpression of the EDN1 gene which play important role in cancer metastasis." (PMID 33995625, 2021). "Based on these properties, EDN-1 and its signaling axis are considered very attractive targets for cancer therapy." (PMID 32194414, 2020). "Endothelin-converting enzyme-1 (ECE1) activates the endothelin-1 peptide, which upregulates pathways that are related to diverse hallmarks of cancer." (PMID 32850305, 2020). "In mammals the EdnrA receptor binds selectively to Edn1 and Edn2, mediates vasoconstriction, and is overexpressed in many cancers)." (PMID 30811380, 2019). "In mice, MSC-secreted IL-6 mediates cancer cells releasing proangiogenic factor endothelin-1 (ET-1)." (PMID 31130595, 2019).
cancer (continued). "We have previously established a reliable animal model of BTcP induced by endothelin-1 (ET-1), which can mimic the clinical manifestations and neurophysiologic changes in cancer patients with BTcP." (PMID 28769766, 2017). "For instance, we determined that EGF and IGF-I, insulin and further tumorigenic factors like hypoxia and endothelin-1 up-regulate GPER expression in diverse cancer cell contexts." (PMID 27384677, 2016). "Endothelin-1 (ET-1) and bradykinin (BK) are two endogenous neuropeptides involved in inflammatory and cancer pain." (PMID 25873305, 2015). "Previously, in a hepatitis B virus X antigen-induced HCC mouse model, we identified genes that were significantly up-regulated at the pre-cancer and cancer stages, including Edn1, Src, Bmp4, and Bmp7." (PMID 24416389, 2014). "The indirect pro-angiogenic effects are for instance related to the secretion of interleukin-6 by MSC that induces endothelin-1 production by cancer cells and thereby enhances endothelial cell recruitment and activation." (PMID 25222747, 2014). "Endothelin-1 (ET-1), a potent vasoconstrictor initially isolated from endothelial cells, is involved in a wide range of cancer-relevant processes, such as inhibition of apoptosis, matrix remodeling, and metastases." (PMID 24727660, 2014). "We also note that in invitro studies in human cancer cell lines EDN1 promotes cell proliferation as well as inhibiting cell death." (PMID 23826316, 2013). "Recent studies have revealed that the endothelin-1 (ET-1)/endothelin A receptor (ETAR) axis is related to the prognosis of cancer patients." (PMID 23987636, 2013). "Endothelin-1 (ET-1) is primarily expressed by endothelial cells but also by cells of certain types of cancer." (PMID 22215065, 2012). "Analyses using the miRanda and Pic Tar algorithms indicated that several cancer-associated genes including MMP11, ERBB2, ERBB3, EDN1, VEGF-A, MMP14 and BCL-9L, were potential target genes of miR-125a." (PMID 22768249, 2012). "Some genes representing the KEGG pathway “Pathways in cancer” (Pdgfra, Pdgfrb, Vegfa, PPP3ca, EphB2 and Prkcn) and the gene ontology term “regulation of transmission of nerve impulses” (Bdnf, Ngfb, Klk8 and Edn1) were also included." (PMID 22384097, 2012). "Cancer cells produce osteoclast inhibitors such as endothelin-1 (ET-1) and osteoprotegerin (OPG)." (PMID 38791037, 2024). "Surprisingly, endothelin-1’s (ET-1) effects on cancer pain are intricate." (PMID 37998446, 2023). "The imbalance expression of EDN1 in cancer development is a well-known event." (PMID 35878242, 2022). "TRPA1 was well-known for mediating histamine-independent itch, including mas-related G protein-coupled receptors (Mrgprs)-mediated itch, oxidative stress-induced itch, endothelin 1 (ET-1)-induced itch, miRNA-711-mediated cancer itch, and 5-HT7 receptor-mediated serotonergic itch." (PMID 35095413, 2021). "CYP24A1 gene was believed to reduce the efficacy of certain anti-proliferative agents such as vitamin D and its analogues 29, and the EDN1 gene that was known to act as a neoangiogenic and mitogenic factor in several cancers 30 are the best target of cancer therapy study." (PMID 33995625, 2021). "Interestingly, podoplanin-positive cancer cell also overexpresses endothelin-1 (ET-1), a promoter of lymphangiogenesis, which supposedly functions by combining ENDRB that expresses on endothelial cells." (PMID 33363035, 2020). "The role of EDN-1 in cancer may be due to over-expression of EDN-1 or overexpression of its receptors, or their signaling pathways." (PMID 32194414, 2020). "Similarly, it contradicts the notion that EDN1 is a proper target when treating progressing cancers." (PMID 32194414, 2020). "Endothelin-1-induced β-arrestin-1 cooperation with transcription factors in cancer cells." (PMID 31551935, 2019). "Furthermore, responses to norepinephrine, endothelin-1, and depolarization with elevated [K+]o were lower in cancer feed arteries compared to control arteries also at pHo 6.8." (PMID 29566737, 2018).
cancer (continued). "Our findings of EDN1 as unique regulator of phenotype heterogeneity maintenance and paracrine protection from BRAF inhibition add a novel feature to EDN1, which is known to be involved in many aspects of cancer development including EMT and chemotherapy resistance." (PMID 28606996, 2017). "In addition, MSC-secreted IL-6 increases cancer cell secretion of endothelin-1 (ET-1), which then stimulates endothelial cells to form new blood vessels." (PMID 26517517, 2015). "Endothelin-1 (ET-1) is a vasoactive peptide that has been also shown to have a role in cancer." (PMID 26543229, 2015). "Endothelin-1 (ET-1) has been involved in many cancer-related processes, such as proliferation, angiogenesis, EMT and metastasis, many of these exerted through activation of multiple signaling cascades, including the Wnt/β-catenin pathway and its known targets such as cyclin D1, MMP2 and survivin." (PMID 26543229, 2015). "To further examine whether the up-regulation of EDN1 is a common feature in various human cancers, we carried out an immunohistochemical analysis on a cancer tissue array." (PMID 24416389, 2014). "Endothelin-1 (ET-1), together with ET-2, ET-3 and the ET receptors (collectively called the endothelin axis), exerts many important physiological roles in normal tissues, as well as in cancer." (PMID 15970923, 2005). "However, overexpression of cancer-related genes; EDN1 and BIRC5 in CSCs have been detected, suggesting that there is another networking pathway which triggering the activation of these genes which led to the enhancement of stemness characteristics of putative CSCs populations." (PMID 33995625, 2021). "Moreover, the expression of EDN1 augments apoptosis in cancer cells induced by mild hyperthermia." (PMID 25932638, 2015). "Similar to periostin, CNN family members are induced by growth factors and cytokines, such as TGF-β and endothelin 1, and cellular stress, including hypoxia, and are overexpressed in pathological conditions that affect connective tissues, including scarring, fibrosis and cancer." (PMID 24273600, 2013). "We thoroughly investigated the biological significance of EDN1/ARRB1 expression with COL1A1 or FN1 by examining their expression levels and predictive value for OS or PFS and SOC cancer staging (stages 1 + 2 or 3 + 4)." (PMID 39985042, 2025). "Next, we identified significantly enriched KEGG (Pathways in cancer and PI3K/Akt signaling pathway) and GO (GO:0000122, GO:0045944 and GO:0045893) terms, and identified eight genes (EDN1, CCND1, MYB, MYC, RUNX1, ITGA6, IL6 and FGF2." (PMID 36978140, 2023). "ET-1 signaling target genes related to cancer progression include CCND1 (Cyclin-D1), AXIN2, PTGS2 (COX2), VEGF, ZEB1, and EDN1 (ET-1) itself." (PMID 38072958, 2023). "The results showed that compared with normal cells (N), the NLRP3, EDN1, HMOX1, and CXCL1 genes were upregulated in the cancer cell group (T)." (PMID 36118079, 2022). "Among Roquin2 targets, we chose four angiogenic genes (ENG, EDN1, VEGFB, and PDGFC) based on two criteria: 1) they are commonly downregulated in different types of cancer cells; and 2) they are among the most affected genes by Roquin2." (PMID 34345214, 2021). "Following RARβ silencing, the down-regulation of cancer-related genes, ALDH1A1, CYP24A1, BIRC5, EDN1, IL-1β and PTGS2 in A549 parental cell suggest the importance of RARβ in controlling the expression of genes related to carcinogenicity." (PMID 33995625, 2021). "Research that has been carried out until now indicates that EDN1 and its receptor (EDNR) are related to cancer progression." (PMID 34829764, 2021). "EDN1, CEBPD, and CTNNB1 are key players in triggering cancer-promoting pathways, including EMT and Wnt/β-catenin signaling pathways." (PMID 34680563, 2021). "In human cancer cells, high expression levels of EDN1 (Endothelin 1) and of endothelin receptors A and B (EDNRA and EDNRB) are associated with the increase of circulating VEGF and of microvessel density." (PMID 30279475, 2018).